BRCA1 (BRCA1 DNA repair associated)
Diseases named in the same sentence as BRCA1 in open-access papers (continued):
Sharing a sentence is not in itself a finding about the gene and the disease.
breast cancer (continued). "Previous clinical studies have revealed that the bacterium secretes cytotoxin-associated gene A antigen, which inhibits the nuclear translocation of the breast cancer susceptibility gene 1 and 2 (BRCA1/2), a factor involved in DNA damage repair." (PMID 39590127, 2024). "The prevalence of the germline PALB2 pathogenic variants was approximately 0.77% in Chinese patients with BRCA1/2-negative early-onset breast cancer." (PMID 38914840, 2024). "Mutations in the FANCA gene have been proven to be linked to a higher possibility of carrying BRCA1/2 mutations and less response to DNA damage, which increase the risk of breast cancer." (PMID 39334297, 2024). "Demographics and clinical characteristics in patients with germline BRCA1/2-mutated HER2-negative advanced breast cancer." (PMID 38817906, 2024). "Women with BRCA1 mutations have an increased lifetime risk of various cancers, including breast cancer (up to 70%) and ovarian cancer (up to 40%)." (PMID 39061909, 2024). "The increased risk of CBC in high-risk breast cancer patients with wild-type BRCA1/2 seems mostly due to having the family history." (PMID 38254240, 2024). "BRCAness refers to HRD due to defects in the HR-associated non-BRCA1/2 genes and is an important marker for the treatment of breast cancer based on synthetic lethal PARPi." (PMID 38745917, 2024). "Early breast cancer HER2-negative patients with high risk of recurrence should be tested for germline BRCA1 and BRCA2 mutations." (PMID 38869741, 2024). "This study aims to assess the cost-effectiveness of talazoparib for treating advanced breast cancer with germline BRCA1/2 mutations and HER2 negativity, considering the perspectives of health services in China and the United States." (PMID 38886516, 2024). "Kuchenbaecker and the BRCA1 and BRCA2 Cohort Consortium9 reported in their study that the cumulative risk of developing breast cancer by age 80 years is 72% for BRCA1 mutation carriers and 69% for BRCA2 mutation carriers." (PMID 38717180, 2024). "Demographics and tumor characteristics of patients with early breast cancer according to pathogenic germline BRCA1/2 mutation (gBRCAm) status." (PMID 39319938, 2024). "Recently, results from the OlympiA trial reported improved survival with the use of poly (adenosine diphosphate-ribose) polymerase inhibitor (PARPi), olaparib in BRCA1/2 mutation associated early breast cancer patients." (PMID 38689097, 2024). "No validation has been conducted for the BOADICEA multifactorial breast cancer risk prediction model specifically in BRCA1/2 pathogenic variant (PV) carriers to date." (PMID 38834293, 2024). "A genetic risk factor can be identified in 5–15% of breast cancers, most commonly mutations in BRCA1 or BRCA2, tumor suppressor genes associated with DNA damage repair." (PMID 38365640, 2024). "BRCA1/2 testing, therefore, can provide a therapeutic opportunity in advanced breast cancer with germline BRCA1/2 mutations and should be performed in this setting, if PARP inhibitors are available." (PMID 38869741, 2024). "Genetic mutations, such as BRCA1 (Breast Cancer Gene 1) and BRCA2 (Breast Cancer Gene 2): Genetic mutations, particularly in BRCA1 and BRCA2 genes, significantly increase hereditary breast cancer risk." (PMID 38699635, 2024). "Among mutation carriers (BRCA1/2) using OCs, an increased risk in breast cancer incidence was observed and this risk persists among short- and long-term users." (PMID 39606555, 2024).
breast cancer (continued). "The study will enrol women, unaffected by cancer, undergoing predictive testing at a familial cancer clinic for a pathogenic variant in a known breast cancer (BC) or ovarian cancer (OC) predisposition gene (BRCA1, BRCA2, PALB2, CHEK2, ATM, RAD51C, RAD51D)." (PMID 39107016, 2024). "Approximately 5% to 10% of breast cancer (BC) cases can be associated with a genetic predisposition, among which BRCA1 and BRCA2 are the most commonly involved genes." (PMID 38564263, 2024). "Among imaging tools, mammography has only 30% of the sensitivity for detecting breast carcinoma in BRCA1/2-mutated carriers (BRCAmut) compared to 83% estimated sensitivity in the general population." (PMID 38792636, 2024). "Up to 10% of all BC cases are estimated to be hereditary with an underlying high breast cancer risk, but only a fraction of BCs is associated with pathogenic variants (PVs) in BRCA1/2 genes." (PMID 39272813, 2024). "LYN is overexpressed in human triple-negative breast cancer (TNBC; the breast cancer subtype most strongly associated with BRCA1 loss) and is also expressed at high levels in mammary tumours from Brca1 conditional knockout mice." (PMID 38149669, 2024). "In the Turkish population, the prevalence of BRCA1/2 mutations in high-risk breast carcinoma patients has been reported to vary between 19 and 37%." (PMID 38753118, 2024). "Genetically predisposed breast cancer (BC) patients represent a minor but clinically meaningful subgroup of the disease, with 25% of all cases associated with actionable variants in BRCA1/2." (PMID 38814507, 2024). "Upregulated expression of BRCA1 and BRCA2 genes was reported in BC and high BRCA1 gene expression was demonstrated to increase the risk of early distant metastasis in ER + breast cancer patients." (PMID 38165507, 2024). "In fact, the most frequent risk factors responsible for BC onset are hereditary and genetic, such as breast cancer or ovarian cancer history and inherited mutations, in particular BRCA1 and BRCA2." (PMID 39141659, 2024). "Pathogenic variants (PVs) in the BRCA1 and/or BRCA2 (BRCA1/2) genes are associated with high risks of developing first and contralateral breast cancer (BC) and ovarian cancer (OC)." (PMID 39446752, 2024). "Expression of VGLL1 and its intronic miRNA miR-934 are associated with sporadic and BRCA1-associated triple negative basal-like breast carcinomas." (PMID 39484215, 2024). "Recent studies have demonstrated that the resistance to treatment with Cisplatin and Adriamycin is caused by the overexpression of BARD1 and BRCA1 in tamoxifen-resistant breast carcinoma cells." (PMID 39274207, 2024). "To date, only one study in Bahrain was conducted to investigate the frequency of germline variants in familial breast cancer women, and it was solely focused on BRCA1/2 gene profiling." (PMID 37656691, 2023). "HDACi can also be used in the therapy of breast cancer associated with mutations in the BRCA1 gene, which is involved in DNA damage repair." (PMID 37108398, 2023). "In our study, 19% (12/63) of the breast cancers had BRCAwt–HRR mutations compared with 6% (4/63) that had BRCA1/2 mutations." (PMID 37173992, 2023). "BRCA1/2 mutations increase the risk of breast cancer almost 6-fold while the risk for ovarian cancer rises about 25-fold over a patient’s lifetime." (PMID 37108225, 2023). "The majority of these breast cancers were in an early stage T1 or T2, with a high proportion of triple-negative tumors in both BRCA1/2-mutated groups." (PMID 37623237, 2023). "In the presence of PARP inhibitors, the PARP-dependent DNA repair system cannot be activated leading to the development of double-strand breaks and susceptibility of BRCA1/2-mutant breast cancer cells for instance to synthetic lethality." (PMID 35976445, 2023). "Combining PD-1/PD-L1 inhibitors with PARP inhibitors in breast cancer with germline BRCA1/2 mutations and ovarian cancer has acceptable toxicity and potential efficacy." (PMID 37345194, 2023).
breast cancer (continued). "Currently, detecting predictive mutations, including BRCA1, is the basis for effectively treating advanced breast cancer." (PMID 37147448, 2023). "FDA has approved two PARP inhibitors, olaparib and talazoparib, for therapeutic use in breast cancers with germline and somatic BRCA1/2 mutations." (PMID 37035242, 2023). "In this work, we show that a panel of miRNAs can be used to identify BRCA1/2 mutation carriers among healthy women with high genetic risk of ovarian or breast cancer." (PMID 37291133, 2023). "Consistently, reconstitution of Gata3 in Gata3- or Brca1-deficient human and mouse mammary tumor cells restores the expression of c-Fos and suppresses Fra1 in inhibiting EMT, motility, invasion, and tumorigenesis." (PMID 37353480, 2023). "According to the Breast Information Core (BIC), most of the breast cancer-causing mutations in the BRCA1 gene lead to the production of a truncated protein that fails to perform its physiological functions." (PMID 37147448, 2023). "Clinical intervention and management for breast cancer patients with BRCA1/2 variants are well established and widely applied in clinical practice." (PMID 37656691, 2023). "Although the somatic mutational landscape, molecular signatures, and HRDetect are well-established in unselected breast cancer, studies of these features among non-BRCA1/BRCA2 high-risk familial breast cancers are limited." (PMID 37316882, 2023). "In term of breast cancer subtype, BRCA1 carriers is typically associated with the TNBC subtype, and hormone receptor‐positive breast cancer is common in BRCA2 carriers." (PMID 35778884, 2023). "ABCB1 genes, also referred to as multidrug resistance (MDR1) genes, encode for p-glycoprotein efflux pumps that are responsible for PARPi resistance, especially in BRCA1-deficient breast cancer and ovarian cancer cell lines." (PMID 37190285, 2023). "Recently, the OlympiA phase 3 trial showed that patients with high-risk, HER2-negative early breast cancer who have germline BRCA1 or BRCA2 pathogenic or likely pathogenic alterations benefited from adjuvant olaparib." (PMID 37173992, 2023). "Here, to address this apparent contradiction, we combined genome-graph analysis of short-read whole-genome sequencing (WGS) profiles across thousands of tumours with deep linked-read WGS of 46 BRCA1- or BRCA2-mutant breast cancers." (PMID 37587346, 2023). "Data from the Gulf Cooperation Council (GCC) states have shown higher rates of BRCA1/2 variants in breast cancer patients." (PMID 37656691, 2023). "High occurrence of breast cancer due to the genetic mutation in BRCA1 and BRCA2 genes in Asian women is directly related to first-degree relatives." (PMID 37886170, 2023). "Hereditary BRCA1 mutations increase the cumulative risk of developing breast cancer by the age of 70 to 60–70%." (PMID 37628606, 2023). "BRCA1/2-mutant breast cancer cells for instance are susceptible to PARPi-induced synthetic lethality." (PMID 35976445, 2023). "The overall survival rate of breast cancer patients with pathogenic BRCA1/2 variants is lower than the survival of non-carriers." (PMID 37173335, 2023). "Another large international retrospective cohort study that included 1236 breast cancer patients with germline BRCA1/2 mutations diagnosed at age ≤40 years examined clinical outcomes associated with each BRCA mutation type and hormone receptor (HR) status." (PMID 36980802, 2023).
breast cancer (continued). "For example, alterations in the breast cancer risk genes BRCA1 and 2 are biomarkers for treatment with poly (ADP-ribose) polymerase (PARP) inhibitors." (PMID 36409394, 2023). "Ashkenazi Jewish people are at higher risk of breast cancer due to the high prevalence of specific founder germline BRCA1/2 variants." (PMID 36612302, 2023). "Approximately 5% to 6% of breast cancers patients carry germline BRCA1/2 (gBRCA1/2) mutations, which are also the most common inherited mutations associated with breast cancer." (PMID 36836123, 2023). "This review has shown that premenopausal women carrying a BRCA1/2 mutation, with an increased risk of developing ovarian or breast cancer, face a challenging process when deciding to undergo a RRSO." (PMID 36826146, 2023). "Breast cancers harboring BRCA1 mutations are characterized by increased PD-L1 and PD-1expression, and a greater immune cells infiltration in the tumor microenvironment." (PMID 37813891, 2023). "The first gene to be identified (in 1994) was BRCA1 which increases a woman's risk for breast cancer (70%) and ovarian cancer (40%)." (PMID 38031144, 2023). "Most commonly, two mutated genes, including breast cancer 1 (BRCA1) and breast cancer 2 (BRCA2) who were inherited, causing ovarian cancer and breast cancer in women." (PMID 36608061, 2023). "Ashkenazi Jewish people are, importantly, at high risk of breast cancer for their inherited cluster with germline BRCA1/2 variants." (PMID 36612302, 2023). "Some studies have reported that breast cancer gene mutations (BRCA1 and 2) can be detected in approximately 5–10% of cases, with 25% of cases occurring in women under the age of 30." (PMID 36900322, 2023). "Based on the mutation frequencies, the magnitude of cancer risk, and the influence on clinical management with mutation carriers, the most important breast cancer susceptibility genes include BRCA1, BRCA2, PALB2, and CHEK2." (PMID 37510234, 2023). "Inheritance of mutations in the breast cancer predisposition BRCA1 or BRCA2 genes carries an elevated risk of breast and ovarian cancer." (PMID 38030626, 2023). "Genes have been identified to significantly increase a woman’s risk of breast cancer (e.g., BRCA1 and BRCA2, with a 70% lifetime risk of breast cancer for the women who carry mutations in these genes)." (PMID 36964875, 2023). "PALB2 is the third most important breast cancer susceptibility gene after BRCA1 and BRCA2, presenting with varying prevalence and mutational profiles in different populations." (PMID 37686625, 2023). "Treatment of MCF-7 breast cancer cells with BRCA1 + NP and BRCA2 + NP was linked with de-phosphorylation (deactivated form) of MAPK without an alteration in the total MAPK level." (PMID 36631481, 2023). "The deleterious mutations of BRCA1/2 are linked to increased risk of malignancy, including breast cancer, ovarian cancer, and ESCC." (PMID 37558683, 2023). "Thai patients with breast cancer with BRCA1/2 mutations were mainly the luminal‐B subtypes with worse prognosis than those without mutations." (PMID 35778884, 2023). "BRCA1, involved in homologous recombination, is one of the most commonly mutated genes in hereditary breast cancer and TNBC (75%)." (PMID 37662839, 2023). "Lee EY found that BRCA1 mutation carriers was mostly diagnosed as TNBC and the risk and survival of breast cancer patients carrying BRCA1 mutations is worse than that of other subtypes of breast cancer." (PMID 36906594, 2023).
breast cancer (continued). "In conclusion, our findings indicate that the associations of height, BMI and weight gain with breast cancer risk in BRCA1 and BRCA2 variant carriers are broadly similar to those reported in the general population when taking into account menopausal status." (PMID 37340476, 2023). "Platinum agents are reportedly more effective for patients with breast cancer carrying germline BRCA1/2 pathogenic variants." (PMID 36865806, 2023). "It is important to emphasize that the impact of these modifiers on breast cancer risk in BRCA1 mutation carriers can vary based on age, family history, and the specific type of mutation." (PMID 37762577, 2023). "Germline mutations in the BRCA1/2 gene have been linked to the development of mammary tumors in female dogs." (PMID 37888559, 2023). "I think, compared to another individual who had a mom who had BRCA1 mutation breast cancer, I definitely have a much lower risk than those individuals...I still have similar risk compared to the regular population, so I’m not worried too much." (PMID 37311883, 2023). "A number of recent studies have shown a higher rate of variants in non-BRCA1/2 genes, and also found differences in the spectrum and prevalence of germline variants in cancer susceptibility gene in breast cancer patients among ethnicities." (PMID 37656691, 2023). "Approximately 5–10% of patients diagnosed with breast cancer have an inherited loss of function in one or both BRCA1 and BRCA2 genes." (PMID 37035242, 2023). "In particular, germline mutations in genes responsible for DNA repair, such as breast cancer susceptibility genes 1 and 2 (BRCA1 and BRCA2), are found to greatly increase an individual’s risk." (PMID 36765666, 2023). "Altogether, our results encourage the use of the PREDICT ER-negative model in management of breast cancer patients with germline BRCA1 variants." (PMID 37173335, 2023). "Several researchers have demonstrated a significant association between BRCA1 mutations and the development of various cancers, including pancreatic, ovarian, prostate, and breast cancers." (PMID 38111536, 2023). "BRCA1-Delta11q is significantly associated with breast cancer resistance to PARPi and cisplatin and patient survival, although inhibition of its splicing can improve sensitivity to PARPi; therefore, it has value as a therapeutic target." (PMID 37771430, 2023). "For example, the genetic sequencing of patients at high risk for breast cancer in the United States has identified BRCA1 and BRCA2 as strong genetic markers." (PMID 37113463, 2023). "Another smaller study, including 44 breast cancer patients revealed the same pattern in the BRCA1 mutational prevalence; BRCA1 c.5266dupC and c.3607C>T, BRCA2 c.9371A>T were also prevalent in this group." (PMID 37239058, 2023). "A recent clinical trial demonstrated that breast cancer patients with germline mutations in BRCA1 or BRCA2 benefit from Poly(adenosine diphosphate–ribose) polymerase (PARP) inhibitor treatment." (PMID 37316882, 2023). "The SETD8 inhibitor has been investigated as a potential therapy for breast cancer associated with the BRCA1 mutation." (PMID 37108398, 2023). "Approximately 25% of patients with TNBC are carriers of breast cancer susceptibility gene 1 or 2 (BRCA1/2) deleterious mutations, which are, in turn, essential components of homologous recombination repair (HRR)." (PMID 37371867, 2023). "Triple‐negative breast cancer (TNBC) is the neoplasia most associated with BRCA1 germline pathogenic variants (PV) and is more likely to develop metastases than the other breast cancer (BC) subtypes, mainly in the lungs and the central nervous system (CNS)." (PMID 37485802, 2023). "This study suggests that aberrant R-loop formation and the subsequent disruption of cell differentiation in breast luminal tissue is one of the causative mechanisms for breast cancer and one of the tissue-specific consequences of BRCA1 mutations." (PMID 37108225, 2023).